USP40 (ubiquitin specific peptidase 40)
Description:
Deubiquitinating enzyme that plays a key role in maintaining endothelial cell (EC) barrier integrity and regulating apoptosis and inflammation. Stabilizes Claudin-1/CLDN1 by cleaving its polyubiquitin chains, thereby protecting tight junction structure. Prevents EC barrier disruption by inhibiting RhoA activation and reducing phosphorylation of myosin light chain and cofilin. Suppresses EC inflammation by inhibiting NF-kappa-B activation, decreasing ICAM1 expression, and reducing leukocyte adhesion to ECs. Mediates these protective effects in part via deubiquitination and inactivation of heat shock protein 90-beta/HSP90AB1. Targets CFLAR for 'Lys-48'-linked deubiquitination, stabilizing its protein levels. This interaction is facilitated by the adapter protein GMEB1, which enhances USP40-CFLAR binding. Through CFLAR stabilization, USP40 inhibits pro-caspase-8 activation and protects against apoptosis.
Synonyms: FLJ10785
Tractability: PROTAC: ubiquitination databases record sites on it.
Gene: Protein-coding gene on chromosome 2 (233,475,526 to 233,566,782, reverse strand). Ensembl gene ENSG00000085982.
Subcellular location: Cytoplasm
Subcellular location (Human Protein Atlas): Vesicles; Focal adhesion sites
Gene Ontology:
Molecular function: cysteine-type deubiquitinase activity
Biological process: negative regulation of apoptotic process; protein deubiquitination
Cellular component: cytoplasm
Genetic constraint (gnomAD): Loss-of-function variants: 121 observed, 129.65 expected, observed/expected ratio (o/e) 0.93, 90% interval 0.8 to 1.09. The upper end of that interval is the gene's LOEUF score, 1.09, which puts it in group 4 of 6, group 1 being the genes least tolerant of losing a copy. Missense variants: 1,280 observed, 1,302.6 expected, observed/expected ratio (o/e) 0.98, 90% interval 0.94 to 1.03. Synonymous variants: 455 observed, 468.65 expected, observed/expected ratio (o/e) 0.97, 90% interval 0.9 to 1.05.
Homologues: Orthologues: chimpanzee USP40 (99% identical), macaque USP40 (94% identical), pig USP40 (84% identical), dog USP40 (83% identical), rabbit USP40 (82% identical), guinea pig USP40 (80% identical), mouse Usp40 (80% identical), rat Usp40 (79% identical), tropical clawed frog usp40 (54% identical), zebrafish usp40 (50% identical). Paralogues in human: USP47 (20% identical), USP31 (11% identical), USP42 (11% identical), USP34 (11% identical), USP36 (11% identical), USP7 (11% identical), USP9X (10% identical), USP48 (10% identical), USP24 (10% identical), USP43 (10% identical), USP9Y (10% identical), USP33 (9% identical), and 59 more.
Diseases named in the same sentence as USP40 in open-access papers:
USP40 is named in the same sentence as 11 diseases in open-access papers, as found by Europe PMC text mining. Sharing a sentence is not in itself a finding about the gene and the disease. The quoted sentences say what the papers report.
hepatocellular carcinoma (2 papers, 2024 to 2025). A malignant tumor that arises from hepatocytes. "Moreover, some studies have reported that USP40 is mainly associated with the transactivation domain of YAP and cleaves the K48-linked polyubiquitination of YAP, thus accelerating hepatocellular carcinoma progression." (PMID 40962058, 2025).
non-small cell lung carcinoma (2 papers, 2019 to 2025). A group of at least three distinct histological types of lung cancer, including non-small cell squamous cell carcinoma, adenocarcinoma, and large cell carcinoma. "GMEB1 can promote the malignant proliferation and metastasis of HCC by promoting the transcription of the YAP1 promoter region; GMEB1 can also interact with USP40 to stabilize CFLARL in non-small cell lung cancer and inhibit cell apoptosis." (PMID 40625743, 2025). "Human non-small cell lung cancer cells and 293FT cells were used to investigate the function of GMEB1/USP40/CFLARL complex by WB, GST Pull-Down Assay, Immunoprecipitation, Immunofluorescence and Flow cytometry analysis." (PMID 31046799, 2019).
Parkinson disease (2 papers, 2008 to 2019). A progressive degenerative disorder of the central nervous system characterized by loss of dopamine producing neurons in the substantia nigra and the presence of Lewy bodies in the substantia nigra and locus coeruleus. "Several reports show that USP40 is correlated with late-onset Parkinson’s disease and USP24." (PMID 31046799, 2019).
Glomerular sclerosis (1 paper, 2023). Accumulation of scar tissue within the glomerulus. "Although Usp40 knockout mice did not exhibit any alterations in the glomerular phenotype, USP40 and its interacting partners formed a regulatory network that protected the cellular processes leading to glomerular sclerosis." (PMID 37509442, 2023).
lung carcinoma (1 paper, 2024). "USP40 has been shown to cleave K48-linked polyubiquitin chains on c-FLIPL in lung cancer cells." (PMID 38307937, 2024).
Sepsis (1 paper, 2024). Sepsis is defined as life-threatening organ dysfunction caused by a dysregulated host response to infection. "The molecular regulation of USP40 expression and activity is anticipated to be a new focus for understanding the processes of inflammatory diseases and developing new therapeutic strategies for acute lung injury and sepsis." (PMID 38307937, 2024).
tumor (2 papers, 2023 to 2024). "In neoplastic diseases, USP40 mutations are associated with clinicopathological features such as poor survival in patients diagnosed with clear cell renal cell carcinoma (ccRCC), and can be used as diagnostic, prognostic and therapeutic markers for ccRCC." (PMID 38308285, 2024). "On the contrary, tumor size and weight were larger in the USP40 overexpression group compared to the control group." (PMID 38308285, 2024). "The findings indicated that the tumor volume and weight were diminished in the USP40 knockdown group compared to the corresponding control group." (PMID 38308285, 2024). "Western blotting analysis of tumor tissues suggested that USP40 knockdown suppressed Claudin1 expression, and USP40 overexpression promoted Claudin1 expression, which was in accordance with the findings of in vitro experiments." (PMID 38308285, 2024). "In this study, our findings elucidated that USP40 exerts tumor-promoting effects by regulating Claudin1 and targeting the USP40-Claudin1 axis is a promising strategy for HCC therapy." (PMID 38308285, 2024). "Through TCGA and UALCAN databases, we discovered that USP40 mRNA was elevated in tumor compared to normal tissues and correlated with tumor stage." (PMID 38308285, 2024). "Finally, western blotting was used to detect USP40 and Claudin1 expression in tumor samples." (PMID 38308285, 2024).
malignant tumors (1 paper, 2024). "USP40 belongs to the USP family, and its role in malignant tumors has been poorly studied." (PMID 38308285, 2024).
USP40 also shares sentences with these, for which no sentence is quoted: colon cancer (1 paper); lung adenocarcinoma (1); membranous nephropathy (1).